UCP1 (uncoupling protein 1)
Diseases named in the same sentence as UCP1 in open-access papers (continued):
Sharing a sentence is not in itself a finding about the gene and the disease.
metabolic disorders (78 papers, 2011 to 2025). "Based on these findings, a mouse model in which the regulatory C253 site on UCP1 is mutated to an alanine (UCP1 C253A mouse) was generated to examine its role in regulating energy homeostasis and metabolic disease." (PMID 37680891, 2023). "The activities of brown-like adipocytes reduce body fat accumulation via induction of thermogenesis associated with UCP1, and result in reduction in the risk of metabolic diseases." (PMID 27598888, 2016). "Additionally, inflammation caused by metabolic disorders negatively regulates UCP1 expression and thermogenic activity in the BAT." (PMID 36467545, 2022). "Upregulation of ACOT2 in females, in conjunction with greater expression of UCP1, suggests that increased thermogenesis is acting as a protection against metabolic disease." (PMID 40181252, 2025). "Oral administration of SP-8356 induced genes related to UCP1-independent energy expenditure in beige adipocytes, and counteracted body weight gain and metabolic disorders in mice." (PMID 39897567, 2025). "Activation of this pathway enhances fatty acid oxidation and UCP1-mediated thermogenesis, offering a therapeutic target for metabolic disorders." (PMID 40362857, 2025). "Given the interest in harnessing UCP1 activity in BAT for treatment of metabolic diseases, our study completes our understanding of UCP1 inhibition by naturally occurring nucleotides." (PMID 40021843, 2025). "This unique function of BAT, achieved by activating UCP1 and other futile cycling mechanisms, makes it an appealing target for therapeutic interventions against metabolic disorders." (PMID 39795975, 2024). "Rhein reduces the expression of LXR target genes, antagonizes the inhibitory effect of LXRs on UCP1, and increases the expression of UCP1 in adipose tissue, thus regulating metabolic disorders." (PMID 39770507, 2024). "Brown and beige adipose tissues need uncoupling protein 1 (UCP1) to execute thermogenesis and Cys253 of UCP1 is sulfenylated during thermogenesis, which provides the strategy to improve therapeutic strategies for combating metabolic disorders." (PMID 37244925, 2023). "Chronic exercise improves the thermogenic capacity to protect against body fat accumulation and other metabolic diseases by suppressing the TGF‐β1/IkB‐α axis in the hypothalamus and causing an over expression of uncoupling protein (UCP1) in obese mice." (PMID 35757424, 2022). "The ability to drive uncoupled respiration through UCP-1 activation represents a possibility in the treatment of metabolic disorders by expending excess energy as dissipated heat." (PMID 33815288, 2021). "Since the discovery of functional BAT in humans, extensive studies have reviewed its role in the context of health and disease, and as a potential target for the treatment for metabolic disease through the activation of UCP1." (PMID 32539124, 2020). "The mechanism studies indicated that the Nrf2 activation by sesamol induces Ucp1 and energy expenditure, leading to the prevention of weight gain and metabolic diseases." (PMID 32443555, 2020). "In the same context, UCP1 overexpression or UCP1 enhancing drugs would be a potential treatment to protect adipose tissues from arsenic-induced metabolic disorders." (PMID 31594991, 2019). "As an uncoupling protein, UCP1 acts in thermogenesis, regulation of energy expenditure, and in decreasing oxidative stress, which are processes deregulated in metabolic disorders." (PMID 29410390, 2018). "Regular exercise has the ability to improve thermogenic capacity by the activation of proteins in the brown adipose tissue such as UCP1, protecting against body fat accumulation and other metabolic diseases." (PMID 28854149, 2017). "Similar to adipocytes in brown adipose tissue, an increase of UCP1-expressing beige adipocytes with thermogenic capacity in white adipose tissue also exerts beneficial effects against metabolic diseases." (PMID 27814392, 2016).
metabolic disorders (continued). "As a critical driver of thermogenesis, UCP1 is regulated mainly at the transcriptional level, and thus the multiple layers of UCP1 regulation bear important relevance to understanding the activation of thermogenesis and its influence on metabolic diseases." (PMID 40324882, 2025). "The results suggest that adipose ApoC2 activation may offer an alternative strategy for controlling UCP1-mediated energy expenditure to combat metabolic disorders." (PMID 39798876, 2025). "However, it has also been suggested that mirabegron can accelerate atherosclerotic plaque development through UCP1-dependent lipolysis, suggesting potential adverse effects in metabolic disorders." (PMID 35241108, 2022). "Furthermore, UCP1 KI pigs represent a model for understanding metabolic disorders and for discovering, validating and optimizing novel therapeutics." (PMID 35096834, 2021). "Remarkably, by the induction of Uncoupling Protein 1, tofacitinib induced the phenomenon of adipocyte browning and/or the emergence of brown-like adipocytes in white adipose depots with consequent relevant metabolic benefits in the treatment of the metabolic diseases." (PMID 38178250, 2024). "Additionally, Akkermansia increased thermogenesis by stimulating uncoupling protein 1 gene expression in brown adipose tissue, improved glucose homeostasis, and ameliorated metabolic disease by stimulating glucagon-like peptide-1 (GLP-1) secretion in C57BL/6 mice after HFD consumption." (PMID 37432375, 2023). "Within these four meta-analyses only A-3826G is examined for its association with metabolic diseases or their risk factors, as the most common variant of UCP1, while these meta-analyses do not consider the associations of other UCP1 SNPs with the risk for disease." (PMID 35482655, 2022). "Same patterns of morphological changes, UCP1 expression and leptin translocation were observed in hADSCs and primary mouse BM-derived stem cells, indicating that MSCs provide a source of thermogenic beige adipocytes for human brown cell-based approaches to treat metabolic diseases." (PMID 29563605, 2018). "This research reveals potential therapeutic targets, such as PKA, AMPK, UCP1 and PGC-1α, which can be used to develop innovative strategies for treating metabolic diseases." (PMID 40244078, 2025). "BAT is known for increasing energy expenditure through the uncoupling protein 1 (UCP1), which reportedly reduces body weight and improves metabolic disorders in obese individuals." (PMID 40076847, 2025). "Brown adipose tissue expresses uncoupling protein 1 (UCP1), which dissipates energy as heat, making it a target for treating metabolic disorders." (PMID 37147287, 2023). "Met or L-car improved metabolic disorders, reduced adipocyte vacuolization and swelling, upregulated levels of BAT-related genes including UCP1 and downregulated proinflammatory marker expressions, and activated the Nrf2/HO-1 pathway in adipose tissues of obese rats." (PMID 38463531, 2024). "Pharmacological intervention to promote brown fat and UCP1 activation, without the need for physiological stimuli, are a therapeutic strategy to combat metabolic disease." (PMID 37256948, 2023). "Uncoupling protein 1 (UCP1) catalyses mitochondrial proton leak in brown adipose tissue to facilitate nutrient oxidation for heat production, and may combat metabolic disease if activated in humans." (PMID 35691529, 2022). "In contrast, global deletion of UCP1 did not recapitulate this phenotype, demonstrating that functional BAT, but not UCP1 itself, is required for the prevention of metabolic disease." (PMID 32539124, 2020). "There is a negative correlation between UCP1 protein levels and insulin resistance in children of mothers of athletes exposed to high-fat diets, indicating that maternal exercise protects against metabolic disorders from children with high-fat diets." (PMID 36093083, 2022).
metabolic disorders (continued). "Our data suggested quercetin could induce the expression and activation of UCP1 in both BAT and WAT to generate metabolic improvements in MetS mice, which implied that quercetin might be a promising drug to activate human BAT against metabolic disorders, but further clinical validation was required." (PMID 39163273, 2024).
infection (14 papers, 2018 to 2024). The state of being infected such as from the introduction of a foreign agent such as serum, vaccine, antigenic substance or organism. "Infection with H. polygyrus suppressed weight gain in obese mice, which was associated with increased uncoupling protein 1 (UCP1) expression in adipocytes and a higher serum norepinephrine (NE) concentration." (PMID 30962398, 2019). "Do BAT and UCP1-dependent thermogenesis contribute to the induction of fever in infection models, such as S.tm?" (PMID 39332526, 2024). "Ten days post infection there was a near complete ablation of STX4 protein with a marked reduction of UCP1 protein concomitant with increased cleaved Caspase1." (PMID 38565851, 2024). "As observed with mouse cells, infection of human adipocytes (differentiated from human primary preadipocytes) did not increase the expression of these genes (with the exception of Ucp1)." (PMID 32409640, 2020). "Consistently, the immunofluorescence staining of UCP-1 in iWAT-SVF-derived matured adipocytes was increased by Lenti-p38αAF infection." (PMID 29750781, 2018). "Infection with H. polygyrus altered the composition of intestinal bacteria, and antibiotic treatment to reduce intestinal bacteria reversed the higher NE concentration, UCP1 expression, and prevention of the weight gain observed after H. polygyrus infection." (PMID 30962398, 2019). "Finally, Ad-ChREBP infection increased white adipose tissue Ucp1 mRNA levels with increased plasma Fgf21 levels." (PMID 30405056, 2018). "Similarly, infection of Lenti-p38αAF increased the mRNA levels of UCP-1 and other thermogenic genes in iWAT-SVF-derived matured adipocytes." (PMID 29750781, 2018). "It is possible that UCP1 is stimulated directly or indirectly by IFN-α in BAT, resulting in the defended elevation of body temperature in response to infection." (PMID 36399061, 2022). "Marked increases of mRNA and protein levels of UCP1 and COX4 were readily detectable 24 h after infection." (PMID 36482111, 2022). "Similar to BAT activation, sWAT also exhibited an overt browning phenotype by high expression of UCP1 and COX4 mRNA and protein 24 h after SARS-CoV-2 infection and became maximally activated after day 3 infection." (PMID 36482111, 2022). "In accordance with previous results, coimmunostaining of UCP1 (BAT marker, red) and GFP (green) confirmed that cold exposure resulted in a denser appearance and higher UCP1 expression of iBAT, with approximately 70% BAT infection in both groups." (PMID 37673898, 2023). "Infection with Hp did not modulate the levels of mRNA for UCP1, IL33 or PPARγ in EWAT of HFD-treated animals at 5 weeks post infection suggesting a minor role of these factors in Hp-associated weight control." (PMID 35499991, 2022). "In the absence of infection, treatment with reserpine significantly reduced the NE concentration and expression of UCP1 in adipose tissue, resulting in increased body weight in mice fed with an ND and an HFD." (PMID 30962398, 2019). "Therefore, UCP1-KO in BAT does not affect LPS-induced body temperature elevation, which does not fully represent the independence of BAT thermogenesis from infection-induced fever." (PMID 36430282, 2022).
neurodegenerative disease (7 papers, 2011 to 2025). A disorder of the central nervous system characterized by gradual and progressive loss of neural tissue and neurologic function. "UCP1 is involved in the regulation of neuronal apoptosis and serves as a potential therapeutic target for treating neurodegenerative diseases." (PMID 40529430, 2025). "Notably, adipocytes transition from a lipid metabolism‐related subtype to one characterized by pathways involved in cell adhesion and neurodegenerative diseases, accompanied by the emergence of a small cluster of Ucp1‐positive adipocytes." (PMID 40631796, 2025). "On the other hand, no similar observations have been reported for AD/D and ALS/MND patients and, indeed, a definitive consensus cannot be drawn about the impact of BAT UCP1 dysfunctions on climate warming and dysregulated thermogenesis in such neurodegenerative diseases." (PMID 36294010, 2022). "It was then not surprising that IPA outputs revealed upstream regulators and master regulators that too have been strongly implicated in neurodegenerative disease such as PPARG coactivator 1 alpha (PPARGC1A) and the mitochondrial uncoupling protein Thermogenin (UCP1)." (PMID 35093178, 2022).
cardiovascular diseases (4 papers, 2019 to 2023). "This review covers the main Ucp SNPs A–3826G, A–1766G, A–112C, Met229Leu, Ala64Thr (Ucp1), Ala55Val, G–866A (Ucp2), and C–55 T (Ucp3), which may be associated with the development of obesity, disturbance in lipid metabolism, T2D, and cardiovascular diseases." (PMID 32450815, 2020).
inflammation (4 papers, 2021 to 2024). Aberrant reaction of the microcirculation characterized by movement of fluid and leukocytes from the blood into extravascular tissues. "Additionally, (i) marathon runners experience NLRP3 inflammasome-related vascular inflammation, in which UCP1 expression may play a role, and (ii) a strong correlation between the upregulation of acute phase proteins and performing world-class/Olympic sports has been found." (PMID 36835062, 2023).
retinopathy (3 papers, 2018 to 2022). "We found that the minor T allele of the missense variation rs45539933 in the UCP1 reduces the risk of retinopathy." (PMID 29410390, 2018).
bacterial infection (1 paper, 2021). "It would be interesting in the future to reproduce our work using Ucp1-knock out mice known to display lowered thermogenic activity, to clearly delineate the role of thermogenesis in pyretic response to bacterial infection." (PMID 34437647, 2021).
neurological disorders (1 paper, 2025). "Evidence has shown that increasing UCP1 expression can inhibit apoptosis and potentially treat neurological disorders." (PMID 40529430, 2025).
UCP1 also shares sentences with these, for which no sentence is quoted: Alzheimer disease (3 papers); hypertriglyceridemia (3); autoimmune hyperthyroidism (2); diabetic cardiomyopathy (2); Impaired glucose tolerance (2); liver disease (2); malnutrition (2); prostate carcinoma (2); adenosis (1); age (1); anemia (1); angiolipoma (1); Atrophy (1); basal cell carcinoma (1); breast invasive cancer (1); cerebral ischemia (1); clear cell sarcoma (1); complication (1); distal motor neuropathy (1); dysferlinopathy (1); endotoxemia (1); glioblastoma (1); helminth infection (1); hepatic cirrhosis (1); hyperprolactinemia (1); hypoadiponectinemia (1); Hypoinsulinemia (1); immune system diseases (1); intestinal cancer (1); intrauterine growth restriction (1).
A further 39 diseases each share a sentence with UCP1 in 1 paper.